LASP1 (LIM and SH3 protein 1)
Diseases named in the same sentence as LASP1 in open-access papers (continued):
Sharing a sentence is not in itself a finding about the gene and the disease.
tumor (continued). "Significant correlations were found between LASP-1 expression and four clinical parameters, including tumor size (P = 0.002), TNM stage (P = 0.005), recurrence status (P = 0.006) and death status (P = 0.026)." (PMID 24955835, 2014). "Using RNA interference, we investigated the effects of LASP-1 depletion on tumor cell behavior in vitro." (PMID 24955835, 2014). "Taken together, the identification of miR-1 as a tumor-suppressive miRNA in human CRC that acts by repressing LASP1 provides x evidence of a pivotal role for miRNAs in CRC tumorigenesis and progression." (PMID 25196260, 2014). "LASP1 is significantly (p=0.028) overexpressed in PCa metastases compared to normal tissues and the primary tumor." (PMID 24980827, 2014). "Our results suggested that overexpression of LASP-1 is linked closely to oral tumourigenicity and further provide novel evidence that LASP-1 plays an essential role in tumor cellular growth by mediating G2/M transition." (PMID 24386158, 2013). "A possible explanation for this discrepancy is that LASP-1 proteins are differently affected by the post-translational ubiquitination and proteolysis in each tumor cell lines." (PMID 24386158, 2013). "In human cancer derived cells, while silencing of LASP-1 resulted in a strong inhibition of cellular growth, overexpression of LASP-1 significantly promoted tumor growth in vivo." (PMID 24386158, 2013). "Among the clinical classifications, the LASP-1 positive OSCCs were correlated significantly (P = 0.02) with tumor size." (PMID 24386158, 2013). "Our previous study demonstrated that tumor suppressive miRNAs, such as miR-1, miR-133a, and miR-145 functioned through repression of LIM and SH3 protein 1 (LASP1), transgelin-2 (TAGLN2), and Switch associated protein 70 (SWAP70)." (PMID 22179486, 2012). "Unexpectedly, we found a high nuclear localisation of LASP-1 in differentiated G1 tumours while in parallel nuclear LASP-1 abundance was correlated with worse prognosis." (PMID 20461080, 2010). "It is possible that tumours with a high nuclear LASP-1-expression represent a subgroup with poor survival irrespective of the grading." (PMID 20461080, 2010). "LASP-1 knock out mice exhibit enhanced wound healing and rapid tumor initiation, consistent with the idea that LASP-1 modulates cell migration." (PMID 20419088, 2010). "In an earlier case–control study, a strong cytoplasmic staining for LASP-1 was detected in >55% of the invasive tumours, which correlated significantly with increased tumour size and rate of nodal-positivity." (PMID 20461080, 2010). "LASP-1 expression was detected in cytoplasm of tumor cells, leukocytes, myoepithelial cells and vascular smooth muscle cells, but not in stromal cells." (PMID 17956604, 2007). "Similarly, in CRC, LINC01123 competitively interacts with miR-625-5p to enhance LASP1 expression, thereby promoting tumor cell invasion and migration." (PMID 40255398, 2025). "As Let-7a is a well-known tumor suppressor miRNA, LASP1 may be an interesting and promising candidate for therapeutic targeting for many types of cancer." (PMID 40863728, 2025). "For instance, miR-1 was early characterized as a tumor-suppressive factor in multiple malignancies, demonstrating its negative role on cell proliferation and migration through the targeting of key genes such as LASP1 and Smad3." (PMID 40871106, 2025). "In this work, based on various cohorts, we assessed the correlations between GLUD1 with IL-32 gene expression levels in HCC tissues, between SYVN1 and LASP1 gene expression levels in HCC tissues, and between GLUD1 gene expression level and tumor size in HBV-associated HCC." (PMID 38587834, 2024).
tumor (continued). "In addition, we have detected the FOXO1/TRIM15/LASP1/AKT loop in tumor samples from HCC patients with TKI sensitive or resistance." (PMID 36670097, 2023). "Biopsies revealed strong LASP1 expression in chordoma and show low expression in less malignant chondrosarcoma supporting the known function of the protein on cell proliferation and migration as seen in other tumor types." (PMID 36497077, 2022). "Moreover, expression of LASP-1 positively correlated with tumor size, poor histological differentiation, lymph node metastasis, advanced TNM stage, and poor prognosis in CCA patients." (PMID 35205774, 2022). "Moreover, circ-CSPP1 and LASP1 levels were remarkably downregulated and miR-431 expression was strikingly upregulated in the tumor tissues derived from the sh-circ-CSPP1-transduced SW480 cells." (PMID 34124372, 2021). "More and more evidence supports LASP1 as a novel tumor metastasis protein." (PMID 34912481, 2021). "Altogether, our data suggest that PUS7 promotes tumour metastasis via LASP1 in CRC cells." (PMID 33990203, 2021). "Therefore, previous studies and our results both indicates that LASP1 acts as a tumor-promoting gene." (PMID 34288804, 2021). "In addition, exo-circ_100395 markedly reduced tumour volume and weight as well as Ki-67 and LASP1 expression in vivo." (PMID 33842488, 2021). "The mechanism by which LASP1 facilitates this invasive ability of tumor cells when CXCR4 is activated is unknown." (PMID 32872485, 2020). "As LASP1 is an adaptor protein it is likely that its loss prevents critical protein-protein interactions downstream in the CXCR4 signaling pathway, leading to the loss of the ability of tumor cells to invade through Matrigel®." (PMID 32872485, 2020). "Previous studies have shown that LASP1 mediates the PI3K/AKT pathway in many tumours." (PMID 31793711, 2020). "LASP1 was previously found to be necessary for CXCR4-dependent tumor cell invasion." (PMID 32872485, 2020). "Additionally, the phosphorylation status of LASP1 affected tumor suppressor microRNA (miRNA) Let-7a-guided Ago2 activity." (PMID 32872485, 2020). "Furthermore, in a large cohort (TCGA, cell 2014), expression of MIAT was positively correlated with LASP1 levels in tumor from 486 patients with PTC (r = 0.292, p < 0.0001)." (PMID 31372094, 2019). "LASP1 mRNA and protein in clinical specimens and tumor cell lines are frequently overexpressed." (PMID 29980193, 2018). "However, LASP-1 exhibits cell-specific inhomogeneous expression patterns in different types of tumours." (PMID 28266596, 2017). "LASP1 over-expression partially abrogated the tumor suppression by miR-203a-3p in NPC cell lines." (PMID 28982387, 2017). "Collectively, miR-203a-3p suppresses tumor growth and metastasis through targeting LASP1 in NPC." (PMID 28982387, 2017). "Lasp1 facilitated tumor proliferation and invasion in multiple cancer entities." (PMID 29088849, 2017). "Knockdown of LASP1 leads to reduced proliferation and migration of these tumor cells." (PMID 27588391, 2016). "Another prominent LASP1 regulating miRNA is the tumor suppressor miR-203." (PMID 25622104, 2015). "For statistical evaluation of tumor samples a LASP1-IRS ≥3 was classified as LASP1-positive." (PMID 26061439, 2015). "In vitro studies showed that LASP-1 plays an important role in tumor development and metastases." (PMID 25760690, 2015). "Concerning LASP-1 and HCC, it is known from global transcriptional profiles of matched pairs of HBV associated HCC tumor and non-tumor liver tissue specimens that LASP-1 is a gene significantly upregulated in this subgroup of HCC." (PMID 25760690, 2015). "Moreover, analysis of 17 specimens of PCa and their corresponding LNM exhibited higher LASP1 levels in metastases, which points to a role of LASP1 in tumor progression." (PMID 24980827, 2014). "Furthermore, the increased expression of LASP-1 correlated significantly with tumor size and lymph node metastasis." (PMID 22897902, 2012).
tumor (continued). "In vitro studies showed that LASP-1 played an important role in tumor development and metastases." (PMID 22897902, 2012). "In this study, we investigated the effect of LASP-1 involved in HBx-related tumor progression." (PMID 22897902, 2012). "Through interaction with these chemokine receptors, LASP-1 may also regulate tumor cell migration or possibly survival." (PMID 20419088, 2010). "Moreover, statistical analysis provided evidence for a positive correlation of cytosolic as well as nuclear LASP-1-positivity with tumor size and nodal-positivity indicating an important role of LASP-1 in proliferation and migration." (PMID 17956604, 2007). "In reverse, tumour cells, that are overexpressing LASP-1, could functionally inhibit zyxin from shuttling into the nucleus and acting as a tumour suppressor through increased recruiting of zyxin to focal contacts by LASP-1." (PMID 17211471, 2007). "However, in LASP1 KD tumours, growth was significantly delayed." (PMID 38789663, 2024). "Hence, the mechanistic comprehension of the HSP90/PUS7/LASP1 axis in CRC metastasis will open novel research opportunities for the elucidation of the functional consequences of PUS7 in the context of tumour development and for the development of new treatment approaches for CRC." (PMID 33990203, 2021). "However, it is unknown which signaling pathway works and how the signal transduces into cell nucleus to drive tumor progression by LASP1." (PMID 34912481, 2021). "In the nucleus, LASP1 stabilizes Snail, a transcriptional repressor of adherens junction proteins, and enables matrix metalloprotease expression by modulating AP-1 transcriptional activity, processes that are involved in mesenchymal cell formation and tumor cell migration." (PMID 32075106, 2020). "Cells transfected with sh-LASP1 had a significantly higher proportion of cells in the G1/G0 phase (P = 0.003) and a significantly lower proportion of cells in the G2/M phase (P = 0.031), which indicated that sh-LASP1 inhibited cell proliferation by arresting the tumor cells at the G1/G0 phase." (PMID 29531214, 2018). "In our study, we found that Lasp1 may promote tumor proliferation and invasion through inducing phosphorylation of FAK (Tyr397) and AKT (Ser473) and thereby upregulate the expression CyclinA2, CyclinB1 and Snail, and downregulating the expression of E-cadherin." (PMID 29088849, 2017). "Our results found that Lasp1 overexpressed in the cytoplasm of NSCLC tissues and associated with larger tumor size, advanced TNM staging and positive lymph node metastasis, suggesting that Lasp1 overexpression may serve as a prognostic marker of NSCLC patients." (PMID 29088849, 2017). "Moreover, we showed that the over-expression of miR-203 could suppress the proliferation and migration of TNBC cells, accompanied by a decrease in the expression of BIRC5 and LASP1, suggesting that miR-203 has tumor-suppressive effects in TNBC." (PMID 22713668, 2012). "In support of this hypothesis, this work shows a cell cycle-dependent increase of nuclear LASP-1 during the mitotic G2/M phase in proliferating tumour cells while serum-starved quiescent cells (G0) as well as cells in G1 and S-phase show only minor levels of the protein in the nucleus." (PMID 20461080, 2010). "Although both proteins are expressed in high levels in the CNS, only LASP-1 seems to be significantly involved in neuronal differentiation upon growth factor stimulation and appears to be of importance in epithelial cancer development regarding tumour cell migration and proliferation." (PMID 18419822, 2008).
tumor (continued). "In CRC, LINC01123 drives tumor progression by regulating miR-34c-5p/VEGFA and miR-625-5p/LASP1 axes." (PMID 40255398, 2025). "It has been reported that LASP1 induces the phosphorylation of FAK-AKT pathway components and negatively regulates PTEN expression in tumor cells, which contributes to hyperactivation of the AKT pathway." (PMID 36670097, 2023). "A total of five potential tumor antigens correlated with prognosis and infiltration of antigen-presenting cells, including AUNIP, FANCI, LASP1, PSMD8, and XPO5 were identified." (PMID 35846349, 2022). "In this study, we identified five tumor antigens (AUNIP, FANCI, LASP1, PSMD8, and XPO5) that were considered promising candidates as mRNA-based vaccines." (PMID 35846349, 2022). "In addition, IHC analysis of a cohort of 56 pairs of CRC specimens (tumour and matched non-malignant tissues) collected from the Xijing Hospital of Digestive Diseases was performed to verify that LASP1 was overexpressed in CRC tissues and positively linked to PUS7." (PMID 33990203, 2021). "In our study, we found that LASP1 was a direct target of miR‐133a and involved in miR‐133a‐modulated NSCLC cell proliferation and tumor growth." (PMID 33074595, 2020). "Concordantly, LASP1 knockdown inhibited cell migration and proliferation in several tumor entities and an indirect regulation of AKT1 by LASP1 was suggested." (PMID 32075106, 2020). "In the current study, we analyzed the newly identified direct phosphorylation-dependent binding of LASP1 to AKT1 and CXCR4, two major players in tumor progression." (PMID 32075106, 2020). "In this study, We confirmed that LASP1 increased the phosphorylation level of PI3K and AKT, treated GBM cells with PI3K/AKT pathway inhibitor LY294002 suppressed tumor growth and enhance the chemosensitivity of TMZ." (PMID 29980193, 2018). "From the determinations of LASP-1 expression levels in all cases of HCC tested, LASP-1 mRNA levels were generally and significantly upregulated in HCCs compared to their adjacent non-tumor counterpart." (PMID 25760690, 2015). "In the current study, we found a high prevalence of increased LASP-1 expression in patients with OSCC and a significant correlation with the primary tumor size." (PMID 24386158, 2013). "H&E staining confirmed the presence of tumor cells in all groups and LASP-1 immunohistochemistry of tumor sections demonstrated LASP-1 knockdown has been maintained in vivo." (PMID 24386158, 2013). "Regarding miR-133a in human cancers, our previous studies demonstrated that miR-133a functions as a tumor suppressor and targets multiple oncogenes, such as FSCN1, LASP1, CAV1 and GSTP1." (PMID 21378409, 2011). "Furthermore, the binding of LASP1 to the tumour suppressor PTEN promotes PI3K/AKT signalling and tumour progression in nasopharyngeal carcinoma." (PMID 38789663, 2024). "AUNIP, FANCI, LASP1, PSMD8, and XPO5 are putative tumor antigens for mRNA vaccine development." (PMID 35846349, 2022). "In hematopoietic cells, LASP1 is not localized to the nucleus assuming an additional cytosolic role of the protein in CML tumor cell persistence and proliferation." (PMID 36497077, 2022). "Upregulation of miRNA-203 strongly repressed tumor cell proliferation, migration, and invasion in TNBC by targeting baculoviral IAP repeat-containing protein 5 (BRIC5) and Lim and SH3 domain protein 1 (LASP1)." (PMID 33916931, 2021). "The expression of LASP1(LIM and SH3 domain protein 1) was upregulated in tumor samples." (PMID 32938459, 2020). "We will summarize the current knowledge through pictorial models and tables including the roles of different microRNAs in the differential regulation of LASP1 levels and patient outcome rather than specify in detail all tumor entities." (PMID 30298118, 2018).
tumor (continued). "Meanwhile, it was reported that miR-133a represses tumor growth and metastasis in CRC by targeting LIM and SH3 protein 1 and inhibiting the MAPK pathway and miR-133a suppresses CRC cell invasion by targeting Fascin1, indicating that miR-133a exerts tumor suppressor functions in CRC." (PMID 30429229, 2018). "Moreover, LASP1 was found to be downregulated after knockdown of PVT1 and overexpression of LASP1 attenuated the tumor-suppressive roles of PVT1 knockdown." (PMID 28404954, 2017). "Lasp1 directly interacted with FAK and facilitated CyclinA2, CyclinB1 and Snail expression, but inhibited E-cadherin expression via phosphorylating FAK-AKT signaling pathway and thereby promoted tumor proliferation and invasion of NSCLC cells." (PMID 29088849, 2017). "Although LASP-1 is found to mediate cell proliferation, migration, and EMT and is associated with poor progression of different types of tumours, the precise molecular functions of LASP-1 are not fully elucidated." (PMID 28266596, 2017). "Therefore, it is plausible that tumor-associated elevations in LASP1 may contribute to LVI, which could explain why we no longer observed a significant hazard ratio when a LASP1 cutoff of 2.1 was used and instead only LVI was found to be a significant predictor of overall survival." (PMID 27799870, 2016). "There was no obvious correlation between LASP1 expression and age, gender, tumor depth (AJCC guidelines) or metastatic spread." (PMID 26061439, 2015). "We confirmed these results via Western blotting analysis of tumor cells expressing AFAP1-AS1 siRNA, and found that RhoA, Rac2, Rab10, Rab11a, Rhogdi and Pfn1 were significantly upregulated, but RhoC, Rab11b and Lasp1 were significantly downregulated in NPC cell lines." (PMID 26246469, 2015). "Real-time PCR was then applied in 20 ccRCC tissues and paired nontumorous tissues, and LASP-1 mRNA levels were also found to be upregulated in tumor tissues." (PMID 24955835, 2014). "The results also revealed increased LASP-1 expression in tumor tissues compared to nontumorous tissues." (PMID 24955835, 2014). "We found that LASP-1 expression was significantly upregulated in the tumor tissues compared to the matched adjacent nontumorous tissues (P<0.0001)." (PMID 24955835, 2014). "To clarify the underlying role of LASP-1 in RCC progression, we first examined the protein expression level of LASP-1 using IHC in 216 tumor tissues and matched adjacent nontumorous tissues." (PMID 24955835, 2014). "Based on this point, we have sequentially identified tumor suppressive miRNAs and miRNA-mediated molecular targets contributing to cancer cell invasion and metastasis, such as miR-1 regulates TAGLN2, miR-145-FSCN1/LASP1, miR-133a-MSN and miR-138-VIM." (PMID 23159910, 2012). "By optimizing the tumor cell motility towards cytokines (including chemokines) and growth factors in the tumor microenvironment (i.e., not random migration), LASP-1 is likely is an important mediator of tumor growth and invasion." (PMID 20419088, 2010). "In a recent case–control study, LASP-1-expression correlated significantly with tumour size and nodal-positivity." (PMID 20461080, 2010). "Although the role of this interaction between LASP-1 and LPP is still unclear, LASP-1 might be embedded into this novel signalling cascade for tumour growth and migration." (PMID 18419822, 2008). "In 89% of all tumor-samples, which were scored to be LASP-1-negative, LASP-1 was not detectable within the nucleus, while 43.5% of all LASP-1-positive specimens showed clear nuclear LASP-1 staining." (PMID 17956604, 2007). "Similar to LASP-1, there is a significant correlation of ENAH-expression and tumor size (p < 0.05)." (PMID 17956604, 2007).